ATR (ATR checkpoint kinase)
Diseases named in the same sentence as ATR in open-access papers (continued):
Sharing a sentence is not in itself a finding about the gene and the disease.
cancer (continued). "Furthermore, a positive correlation was detected between TOPBP1 expression and the ATR pathway in the cellular context of PDAC cancer cell lines." (PMID 39920847, 2025). "Indeed, many cancers are often reliant on these proteins for continued proliferation, and ATR and ATM inhibitors are in clinical trials for a variety of malignancies." (PMID 40514450, 2025). "Six of these PGVs were in cancer predisposition genes (ATR, CHEK2 (3x), SDHA and MITF) without an established association with familial glioblastoma." (PMID 41168197, 2025). "Our work defines an ATR-independent, scaffolding role for the 9-1-1 complex in ssDNA gap protection, revealing a fundamental mechanism of replication stress tolerance and a new therapeutic vulnerability in BRCA2-deficient cancers." (PMID 41278922, 2025). "Importantly, our data reveal a similar relationship between AEP and ATR levels not only in BC, but also in other types of cancer." (PMID 40012043, 2025). "Therefore, inhibition of the ATR pathway using ATR inhibitors or RNA splicing perturbation by expression of the spliceosome mutant results in cancer cell death due to catastrophic DNA damage, indicating a potential vulnerability." (PMID 40332372, 2025). "ATR is both an oncogene and a tumor suppressor in the context of cancer." (PMID 40940791, 2025). "Altogether, these findings suggest that ATR inhibition may overcome oxaliplatin resistance by acting directly on cancer cells, while simultaneously increasing the antitumor immune response." (PMID 40139833, 2025). "Consistent with the ATR-LSS axis promoting mTORC1 activity via cholesterol in p16 knockdown cancer cells, knockdown or inhibition of either ATR or LSS decreased mTORC1 activity, and these effects were rescued by supplementation with either lanosterol or cholesterol." (PMID 40514450, 2025). "Targeting ATR represents a promising strategy for treating cancers." (PMID 39941729, 2025). "Consequently, ATR has emerged as a promising target in cancer therapy, with researchers investigating its synthetic lethal potential in a manner analogous to the relationship between PARP inhibitors and HRD." (PMID 40859871, 2025). "Furthermore, the combined efficacy of IMPDH and ATR inhibition warrants further investigation more broadly in cancer." (PMID 40491496, 2025). "Since cancer cells depend on an effective RS response for their survival, considerable effort has been made to develop small-molecule inhibitors of the intra-S checkpoint kinases ATR, CHK1, and WEE1." (PMID 39887032, 2025). "Together, this likely indicates that cholesterol metabolism may have pleotropic effects on these cells and point to a multifaceted role for the ATR-LSS axis in cancer biology." (PMID 40514450, 2025). "Nevertheless, abundant evidence underscore the impact of ATR overexpression on cancer progression." (PMID 40256842, 2025). "In addition, recent studies have demonstrated that activation of ATM/ATR/Chk1 kinase in response to DNA double-strand breaks by irradiation can enhance PD-L1 expression in cancer cells." (PMID 39001550, 2024). "This hypoxia‐selective release of AZD6738 inhibited ATR activation (T1989 and S428 phosphorylation) and subsequently abrogated HIF1a‐mediated adaptation of hypoxic cancers cells, thus selectively inducing cell death in 2D and 3D cancer models." (PMID 38976561, 2024). "Moreover, targeting specific checkpoints in the cell cycle with inhibitors like Chk1/2 and ATR has shown potential in sensitizing cancer cells to DNA-damaging agents." (PMID 39458945, 2024). "This led us to unravel that ATM and ATR inhibitors represent a strategy particularly suited to jeopardize DDR in acid-exposed cancer cells and exert growth inhibitory effects on this aggressive tumor compartment either as a single agent or in combination with chemotherapy." (PMID 38366255, 2024). "Moreover, activated ATR signaling with the loss of KDM5D expression can be exploited to elicit synthetic lethality of ATR inhibition in cancer cells." (PMID 37974379, 2024).
cancer (continued). "Thus, targeting this pathway is a viable therapeutic strategy for the treatment of cancer and has resulted in the clinical evaluation of a plethora of ATR inhibitors (ATRi) that target the kinase domain for competitive inhibition." (PMID 39108493, 2024). "Importantly, short treatments with ATM and ATR inhibitors in cultured cells increased the levels of cancer-specific rearrangements." (PMID 38773641, 2024). "Therefore, inhibition of the ATR pathway is an attractive therapeutic approach for patients with cancer." (PMID 38287179, 2024). "The rationale behind targeting ATR in cancer is that the inhibition of ATR may lead to genomic instability, DSBs, and replication fork collapse." (PMID 39271762, 2024). "BAY1895344, another novel potent and selective ATR inhibitor, exhibits strong monotherapy efficacy in cancers, and synergistic activity in combination with DNA damage therapies.1265 A phase II clinical trial of BAY1895344 in patients with recurrent solid tumors (NCT05071209) is in progress." (PMID 38763973, 2024). "The stable protein associations at the mitochondria between tBid and anti-apoptotic mitochondrial ATR play a crucial role in maintaining the viability of cancer cells, suggesting a novel mechanism to induce cancer cell apoptosis by freeing tBid from the ATR associations at mitochondria." (PMID 38927905, 2024). "Therefore, targeting ATR with pharmacological inhibitors is an attractive approach to radiosensitize cancer cells." (PMID 39235982, 2024). "To test whether our data initially obtained in DLD-1 were generalizable beyond one cell line or tumor entity, we next assessed whether POLA1 depletion also sensitized other cancer cell lines towards ATR/CHK1-inhibition." (PMID 39128273, 2024). "Preclinical studies have also shown that ATR inhibition increases platinum sensitivity in platinum-resistant cancer cells and may also enhance sensitivity to other chemotherapeutics." (PMID 38287179, 2024). "ATM and ATR inhibitors can also be used for the treatment of ALT-positive cancers." (PMID 38910895, 2024). "Therefore, ATM and ATR inhibitors are also used in cancer therapy to treat patients with ALT-positive cancers." (PMID 38910895, 2024). "It showed single-agent activity, as well as synergistic activity in combination with cisplatin, especially in advanced cancers with ATM aberrations confirming synthetically lethal interaction between ATM deficiency and ATR inhibition during the phase 1 clinical studies." (PMID 38279263, 2024). "Similarly, a previous cell line study also reported a relationship between APOBEC3B overexpression and anti-cancer activity of ATR inhibition." (PMID 38827321, 2024). "Synthetic lethal approaches being investigated in tumor-agnostic studies include PARP inhibitors for BRCA1/2- or ATM-mutant cancers; ATR inhibitors for ATM-mutant cancers; and PKMYT1 inhibition for solid tumors with CCNE1 amplification, FBXW7 loss, and PPP2R1A mutations (NCT04855656)." (PMID 38938274, 2024). "Inhibition of ATR sensitizes cancer cells to photons and protons." (PMID 39235982, 2024). "Additionally, at least, in certain cancers such as prostate carcinoma inhibition of CDK8/19 led to increased ATR-dependent RS and DNA damage by inducing aberrant G1/S transition." (PMID 38279263, 2024). "Following mutation or other inactivation of the checkpoint kinases ATR and CHK1 during tumourigenesis, these replication-associated DNA lesions may lead to loss of genomic integrity and cancer development." (PMID 38331839, 2024). "Consequently, inhibition of ATR would indirectly deplete dNTP pools and hence limit cancer progression." (PMID 39206868, 2024).
cancer (continued). "Furthermore, although cancer cells treated with VE-821, another ATR inhibitor, were sensitized to carbon ion irradiation (LET: 70 keV/μm), the sensitization enhancement ratio (SER) was slightly lower than that seen for X-rays." (PMID 38920686, 2024). "Combining ATR and PARP inhibitors potentiates the cell death of ATM-deficient cancer cells, which may benefit immunotherapy treatment." (PMID 38630271, 2024). "Hence, inhibiting DDR by targeting ATR has been proposed as a new strategy for cancer therapy, especially in cancer types that have genomic instability due to high replication stress levels." (PMID 38756373, 2024). "Therefore, inhibiting ATR is expected to radiosensitize more cancer cells, which have defective G1 checkpoint, than normal cells, which have intact G1 checkpoint." (PMID 39235982, 2024). "One emerging approach in cancer treatment including HNSCC involves the use of small molecule kinase inhibitors (smKI) targeting Ataxia telangiectasia mutated (ATM) or Ataxia telangiectasia mutated and Rad3-related (ATR) kinases." (PMID 39411143, 2024). "Therefore, to minimize the side effects of the combination of PARP and ATR inhibitors, further investigation in a clinical trial to evaluate the safety and efficacy in cancer patients is required." (PMID 36794257, 2023). "However, those cancer cells still have activated G2 checkpoint, a chromatin-quality checkpoint in late G2 involving ATR/p38MAPK/MK2." (PMID 37740222, 2023). "Whether this suggests that primary and stem cells might be more sensitive to ATR inhibition than cancer cells requires further investigation." (PMID 37336885, 2023). "ATR is a promising therapeutic target in cancer cells because its inhibition could lead to an accumulation of damaged DNA preventing further replication and division." (PMID 36604210, 2023). "The ATR checkpoint is also responsive to replication stress, one of the hallmarks of cancer." (PMID 37390209, 2023). "The use of VE‐822 may inhibit ATR‐Chk1 signaling and thus achieve reversal of cisplatin resistance in some cancers." (PMID 37502611, 2023). "Selectively moderating the levels of ATR kinase (trans-ATR) and antiapoptotic cis-ATR could be a potential strategy for enhancing cancer therapies." (PMID 37511442, 2023). "Inhibition of WEE1 by AZD1775 has also been shown to induce p-S345-CHK1 by activating ATR in other cancer cells, which may circumvent the effectiveness of WEE1 inhibition." (PMID 37987002, 2023). "The RPA heterotrimers are downstream of the ATR substrate and may be a considerable pharmacological target for cancer therapy." (PMID 37858134, 2023). "Therefore, it is clinically important to characterize pathogenic ATM/ATR mutations, which would in turn help infer the involvement of other variants of uncertain significance of these two PIKK genes in cancer." (PMID 38041093, 2023). "This work demonstrates the evidence that supports the development of cancer therapy through the combination strategy of PARP and ATR inhibitors, and assesses HRR deficiency as predictive biomarkers to identify individuals tending to respond to PARP and ATR inhibitor combination treatments." (PMID 36794257, 2023). "Given the rapid emergence of resistance to monotherapy in cancer, we investigated whether combination BRD4i with WEE1 or ATR inhibition would be a strategy to exploit ARID1A loss by targeting two critical pathways critical for survival." (PMID 37841875, 2023). "Ataxia telangiectasia–mutated (ATM serine/threonine kinase) is a further apical kinase of DNA DSB response, that signals in a partially nonredundant fashion with ATR, and ATR inhibitors have synthetic lethal activity in ATM-deficient cancers." (PMID 37773077, 2023). "In recent years, NU6027, NVP-46BEZ235, Torin 2, and ETP-46464 have been reported to be more potent ATR inhibitors that have been shown to sensitize cancer cells to a variety of genotoxic chemotherapies but have also inhibited other kinases such as CDK2, PIK3, mTOR, and ATM." (PMID 37511442, 2023).
cancer (continued). "Some studies have demonstrated that ALT cancers may be more sensitive to ATR inhibition compared to telomerase positive cancers." (PMID 36833275, 2023). "However, the development of cancer therapy targeting the ATR signaling cascade was initially focused on CHK1 inhibitors rather than the ATR kinase itself." (PMID 36902170, 2023). "Since ARID1A mutation cells induce upregulation of ATR, blocking ATR activity could work as an ICC treatment by reducing cancer cell survival." (PMID 38203635, 2023). "Indeed, several previous studies in human immortalized or cancer cells have suggested a function of ATR and CHK1 in controlling replication initiation and origin firing by counteracting CDC7 or CDK1 activties." (PMID 37336885, 2023). "Concerning cancer cells suffering from replication stress, it may confer a window for pharmacological ATR inhibition." (PMID 37679326, 2023). "Indeed, targeting CCNE1-high cancers with inhibitors of the ATR signaling pathway is a well-studied strategy." (PMID 38032106, 2023). "Cancer initiation and transformation has been closely linked with oxidative stress and inflammation, thus the role of APE2 in ATR activation may be a critical determinant in the prevention of tumor cell formation." (PMID 36755963, 2023). "Anticancer medicines such as DNA-damaging methylating/alkylating compounds and topoisomerase inhibitors that activate ATR through phytochemicals may sensitize cancer cells." (PMID 37511442, 2023). "However, ATR functions appear to be even more critical for survival of cancer cells with activated oncogenes such as RAS, MYC and Cyclin E which themselves disrupt the normal cell cycle regulation generating high level of RS." (PMID 36749285, 2023). "Replication stress is a cancer-specific vulnerability that can be exploited through inhibition of S-phase checkpoint kinases such as ATR and CHK1 among other therapeutic agents that can enhance replication stress and push cancer cells toward mitotic catastrophe." (PMID 37475004, 2023). "ATM and ATR are activated by oncogenic stresses, suggesting that cancer cells may rely on DNA damage response pathways to survive genomic instability." (PMID 37298208, 2023). "ScaRNA2 was identified as the most abundant lncRNA bound to ATR and was demonstrated to bridge DNA end resection to ATR activation; thus, it could be applied as a potent target for combined cancer treatments with chemoradiotherapy." (PMID 37775817, 2023). "In turn, ATR inhibition is particularly toxic to cancer cells with an accumulation of R-loops." (PMID 37108225, 2023). "Uncovering the mechanism of ATR activation may provide novel opportunities and targets for improving cancer therapy." (PMID 37775817, 2023). "This might be a possible pharmaceutical target for controlling the mitochondria linked with ATR through phosphatase PP2A, which could lead to novel treatment techniques for apoptotic cell death and cancer." (PMID 37511442, 2023). "Preclinical models have shown that TNBC, BRCA mutant and ATM-deficient cancer may be highly sensitive to the combination of PARP inhibitors and DNA damage response kinase inhibitors such as ATR inhibitors." (PMID 37773077, 2023). "Interestingly, some of the players involved in DNA repair, such as ATR, are less relevant in healthy normal tissues, but become a specific vulnerability of cancer cells in the setting of high DNA damage burden." (PMID 37627183, 2023). "This stage-specific effect of ATR on productive DNA replication may provide a means to dose ATR inhibitors to minimize normal tissue toxicity during cancer therapy." (PMID 37336885, 2023). "Interestingly, pan-cancer cohort analysis indicated that KRAS-mutant patients with high ATR expression (389/907, 42.9%) had a significantly lower OS rate than patients with low ATR expression." (PMID 37591859, 2023).
cancer (continued). "This variant is absent from the gnomAD database (gnomAD v2.1.1 non cancer) and the observed/expected score for loss of function of ATR is 0.31 (90% CI: 0.24–0.4)." (PMID 36749285, 2023). "However, various studies revealing CHK1 overexpression or ATR-independent CHK1 activation in cancer make CHK1 an independent target for cancer therapy." (PMID 37445667, 2023). "These lower somatic variants burden and presence of gene amplifications could also reflect the essential role of ATR in cancer cells." (PMID 36749285, 2023). "Such a protein target that is novel and effective in the treatment of cancer could be cis-ATR (ATR-H), potentially." (PMID 37511442, 2023). "Considering the essential function of ATR in controlling genome integrity, it could be important to enhance cancer surveillance in ATR Seckel patients (carrier of constitutional homozygous or compound-heterozygous hypomorphic variants of ATR)." (PMID 36749285, 2023). "Finally, novel strategies targeting the ATR-scaRNA2 complex need to be developed for use in clinical cancer treatment." (PMID 37775817, 2023). "The distinct functions of cis- and trans-ATR require a delicate balance of the levels of these two forms to ensure cellular homeostasis that prevents cis-ATR being exploited by cancer cells for their survival while maintaining genome integrity and stability in normal cells." (PMID 37508437, 2023). "Moreover, previously studies revealed a significant response to ATR inhibitors in cancer cells which rely on alternative lengthening of telomeres (ALT) to overcome replicative mortality." (PMID 36269546, 2022). "Furthermore, APOBEC signatures have been associated with sensitivity to ataxia telangiectasia and Rad3-related kinase (ATR) in some cancer cell lines, suggesting a potential for targeted therapy." (PMID 36291592, 2022). "Besides, our study represents a proof of concept to use the ATR mutational status as predictive chemosensitivity biomarker to topoisomerase I and ATR inhibitors in cancer therapy." (PMID 35361811, 2022). "ATR inhibition has been shown to disrupt BRCA1-independent loading of RAD51 at DSBs causing stalled forks and to be effective in overcoming resistance to PARP inhibitor in cancer cells exhibiting BRCAness." (PMID 36123603, 2022). "VE-821, another ATR inhibitor, successfully sensitized bone and ovarian cancer cells to radiation in vitro, forcing irradiated cells to divide into daughter cells and decreased survival selectively in cancer cells." (PMID 36499000, 2022). "In addition, ATR inhibitors paired with genotoxic chemotherapeutics or radiotherapy have synergistic activity in numerous cancer cells." (PMID 36539893, 2022). "Similarly, inhibition of other HRR genes, such as ATM and ATR, leads to BRCAness and sensitizes cancer cells to PARP inhibitors." (PMID 35328658, 2022). "Hence, ATR inhibitors are likely to present a synthetic lethal strategy to target cancer cells with mutant or low ARID1A expression." (PMID 36249060, 2022). "In short, ssDNA damage response mediated by ATR/Chk1 may govern the sensitivity of cancer cells to TOP1 inhibitors." (PMID 35844787, 2022). "Though further work is required to draw concrete mechanistic conclusions between replication stress, MMR, and ATR activation, our study provides evidence for the individual roles of MMR proteins in ATR activation upon TMZ treatment in MGMT-promoter methylated cancer cells." (PMID 35388070, 2022). "In addition, ATR inhibitors have been reported to synergize with CX-5461 and the combination exhibits more robust cancer cell killing of leukemia cells." (PMID 35053227, 2022).